KRT14 (keratin 14)
Diseases named in the same sentence as KRT14 in open-access papers (continued):
Sharing a sentence is not in itself a finding about the gene and the disease.
amelogenesis imperfecta (2 papers, 2017 to 2021). Amelogenesis imperfecta (AI) represents a group of developmental conditions affecting the structure and clinical appearance of the enamel of all or nearly all the teeth in a more or less equal manner, and which may be associated with morphologic or biochemical changes elsewhere in the body. "Conditional deletion of BMP2 and BMP4 using K14-cre mice (which have keratin-14 promoter-driven cre recombinase) resulted in amelogenesis imperfecta caused by downregulation of the removal of enamel matrix protein during maturation." (PMID 29273814, 2017).
cholesteatoma (2 papers, 2018 to 2021). A pathologic process characterized by the proliferation of keratinizing squamous epithelium resulting in the accumulation of keratin and cells in the middle ear and/or mastoid. "Furthermore cytokeratin 14, which is regularly expressed in mitotically active basal layer cells in normal skin and cholesteatoma, is expressed in cholesteatoma tissue in a higher extend compared to normal auditory canal skin." (PMID 33627146, 2021).
ductal carcinoma (2 papers, 2001 to 2014). "2–18% of ductal carcinoma-No Special Type (NST) are reported to express basal cell keratin 14 and such tumours may have a different metastatic pattern and prognosis." (PMID 11487275, 2001).
epidermolytic palmoplantar keratoderma (2 papers, 2023 to 2025). "Severe EBS results from mutations in KRT5 and KRT14 and is characterised by skin fragility, herpetiform blistering, and the development of confluent palmoplantar keratoderma and nail dystrophy." (PMID 40700032, 2025).
Erythema (2 papers, 2022 to 2024). Redness of the skin, caused by hyperemia of the capillaries in the lower layers of the skin. "PT11 and PT12 (heterozygous mutation c.373C > T, p.Arg125Cys in KRT14) had herpetiform blistering and crusting with erythema on the trunk and extremities, as well as moderate to severe keratoderma on the soles." (PMID 36578049, 2022).
Gastric tumors (2 papers, 2010 to 2016). "To confirm the universality of these expression changes, we measured the levels of CXCR2, KRT14 and TNF-α in SGC 7901 cells, which are also derived from gastric tumors." (PMID 27556695, 2016). "The current study found that stimulation of PADI4 increased CXCR2, KRT14 and TNF-α expression levels, suggesting that increased expression of PADI4 in gastric tumor tissues, as we previously observed, contributes to tumorigenesis by increasing the expression levels of CXCR2, KRT14 and TNF-α." (PMID 27556695, 2016).
hepatocellular carcinoma (2 papers, 2022 to 2024). A malignant tumor that arises from hepatocytes. "There is currently only one report that suggests KRT19 as a CSC marker in hepatocellular carcinoma (HCC), while another recent study demonstrated that inter-keratin fusions between KRT6 and KRT14 could promote cancer stemness in OSCC." (PMID 35706019, 2022).
ichthyosis (2 papers, 2017 to 2018). Disorders of cornification that are characterized by visible scaling and/or hyperkeratosis of most or all of the skin. "Here we generated a novel, viable, and fertile mouse (Cx26CK14-S17F/+) with the keratitis-ichthyosis-deafness mutant (Cx26S17F) driven by the cytokeratin 14 promoter." (PMID 28569788, 2017).
keloid (2 papers, 2017 to 2022). An irregularly shaped, elevated mark on the skin caused by deposits of excessive amounts of collagen during wound healing. "It meant, transcriptional levels of three array-up-regulated lncRNAs and three of their paired Wnt-genes, named CACNA1G-AS1/MMP2, HOXA11-AS/CDKN2A and LINC00312/KRT14, were significantly changed in keloids by intracellular qPCR measurement, simultaneously." (PMID 28404955, 2017). "Most keratins were downregulated in keloids, including KRT10, KRT14, KRT15, KRT19, KRT1, KRT77, and KRT5." (PMID 35435317, 2022).
Myoepithelial carcinoma (2 papers, 2023 to 2025). "Immunohistochemistry is crucial in distinguishing myoepithelial carcinomas from other tumors, with markers like S100, actin, or cytokeratin 14 being commonly expressed." (PMID 41368055, 2025). "Myoepithelial carcinoma usually stains positive for high molecular weight cytokeratins (AE1/AE3, KRT14) and myoepithelial markers, such as smooth muscle actin (SMA), p63, S100, GFAP, and calponin." (PMID 37705036, 2023).
nodular melanoma (2 papers, 2021 to 2024). "In the case of nodular melanoma, an increased thickness of the epidermis was reported in 90% of biopsies and was associated with aberrant suprabasal expression of keratin 14 (KRT14) in the proximal epidermis." (PMID 39201498, 2024). "In nodular melanoma, KRT14 was found strongly present in basal layer as well as in suprabasal cells." (PMID 33441834, 2021).
sebaceous tumors (2 papers, 2013 to 2015). "Human sebaceous tumors have been reported to contain LEF-1 N-terminal domain mutations with decreased ability to interact with β-catenin, and expression of a LEF1 construct lacking the first 32 aa driven by the keratin 14 promoter provoked the formation of sebaceous skin tumors in mice." (PMID 23966864, 2013).
Sepsis (2 papers, 2023 to 2024). Sepsis is defined as life-threatening organ dysfunction caused by a dysregulated host response to infection. "One of the main causes of death for patients with KRT14 variants is sepsis; additionally, individuals who have c.377T > A variant, appear to be much more susceptible to infection than those with c.6163G > A variant." (PMID 38580989, 2024). "KRT14 variants cause sepsis, and c.377T > A variants increase infection susceptibility than c.6163G > A variant." (PMID 38580989, 2024).
skin papilloma (2 papers, 2015 to 2016). A benign papillary neoplastic growth on the skin composed of epithelial cells and a fibrous stalk. "The skin papilloma formation of Tg(krt14:MEK2S219D-GFP) was presented approximately 34 % in homozygous and 5 % in heterozygous." (PMID 26572230, 2015). "Treatment with 50 μM of the MEK inhibitor, U0126, had significantly decreased the skin papilloma formation in Tg(krt14:MEK2S219D-GFP) zebrafish by 6 dpf." (PMID 26572230, 2015). "We further examined whether skin papilloma formation in Tg(krt14:MEK2S219D-GFP) zebrafish was induced by MEK2 activation by specific MEK1/2 inhibitor, U0126." (PMID 26572230, 2015). "The transgenic zebrafish, Tg(krt14:MEK2S219D-GFP), developed skin papillomas in the epidermis within 6 days post-fertilization (dpf)." (PMID 26572230, 2015). "No skin papilloma was observed at 2 dpf in Tg(krt14:MEK2S219D-GFP) zebrafish larvae." (PMID 26572230, 2015). "Incubated Tg(krt14:MEK2S219D-GFP) zebrafish larvae with 50 μM at 2 dpf or 0.01 % DMSO as control, no skin papilloma was observed in U0126 treatment at 6 dpf but several skin papilloma was observed in DMSO treatment at 6 dpf." (PMID 26572230, 2015).
squamous papilloma (2 papers, 2011 to 2022). A benign epithelial neoplasm characterized by a papillary growth pattern and a proliferation of neoplastic squamous cells without morphologic evidence of malignancy. "We previously showed that mice expressing a tamoxifen-inducible Cre recombinase under the control of the cytokeratin 14 (K14) promoter, finally expressing an oncogenic mutation of K-ras (LSL-K-rasG12D mice), develop squamous papilloma in the oral cavity within 1 month from tamoxifen treatment." (PMID 35409002, 2022).
thymoma (2 papers, 2015 to 2024). A neoplasm arising from the epithelial cells of the thymus. "KRT6A and KRT17, commonly used markers for the detection of thymoma, were not significantly overexpressed in the malignant cell populations; Only KRT14 was found overexpressed in the malignant mcTEC subpopulation." (PMID 39258580, 2024).
thyroid cancer (2 papers, 2018 to 2022). "Subsequently, the TCGA database results showed the expression of CXCL10, CD40LG, KRT14, TRAT1, and TREM2, with only TREM2 expression levels being upregulated in thyroid cancer (P < 0.05)." (PMID 36438899, 2022). "Subsequently, TCGA database results showed the expression of CXCL10, CD40LG, KRT14, TRAT1, and TREM2, with only TREM2 expression levels being upregulated in thyroid cancer." (PMID 36438899, 2022). "By targeting cytokeratin 14 RNA with ultrabright SERS nanorattles, we demonstrated the capability of our method in distinguishing HNSCC from other tissue types such as thyroid cancer and benign lymphoid tissue." (PMID 30061592, 2018).
type 2 diabetes (2 papers, 2021 to 2024). "Finally, single-gene validation and receptor operating characteristic analysis revealed that four of these genes (MMP12, PLAU, KRT14, and DKK1) may be involved in the common pathogenetic mechanism of adamantinomatous craniopharyngioma and type 2 diabetes." (PMID 38848397, 2024).
vitiligo (2 papers, 2021 to 2025). Generalized well circumscribed patches of leukoderma that are generally distributed over symmetric body locations and is due to autoimmune destruction of melanocytes. "To investigate whether CCL17 is critical for depigmentation, we adoptively transferred CFP‐PMEL CD8+ T cells into wild type (WT) or CCL17‐deficient (CCL17−/−) KRT14‐Kitl*4XTG2Bjl (Krt14‐Kitl*) mice to induce vitiligo." (PMID 34077992, 2021). "To investigate whether CCR4 is critical for depigmentation, we adoptively transferred CFP‐PMEL CD8+ T cells (WT) or CCR4‐deficient CFP‐PMEL CD8+ T cells (CCR4−/−) into KRT14‐Kitl*4XTG2Bjl (Krt14‐Kitl*) mice to induce vitiligo." (PMID 34077992, 2021).
acute respiratory distress syndrome (1 paper, 2021). Progressive and life-threatening pulmonary distress in the absence of an underlying pulmonary condition, usually following major trauma or surgery. "Krt14 is highly upregulated in proliferating cells including hyperplastic alveolar cells seen in the diffuse alveolar damage of acute respiratory distress syndrome patients, bronchiolar metaplastic cells and in areas of more severe fibrosis in IPF patients." (PMID 34678949, 2021).
anemia (1 paper, 2024). A reduction in the number of red blood cells, the amount of hemoglobin, and/or the volume of packed red blood cells. "Regarding the 6 patients with variants in KRT14 gene, all of them also presented blistering in the first days of life and half manifested sweating and anemia during early childhood, but curiously none complained about itching; none had pseudo syndactyly or milia." (PMID 38368142, 2024).
aplasia cutis congenita (1 paper, 2024). Aplasia cutis congenita (ACC) is a rare skin disorder characterized by localized absence of skin that is usually located on the scalp but can occur anywhere on the body including the face, trunk and extremities. "Furthermore, unlike our KRT14 patient, the COL7A1 patient had Aplasia cutis Congenita and skin absence at birth, which is a defining marker of DDEB." (PMID 38580989, 2024).
astrocytoma (1 paper, 2022). "Except for CCND2, FLT1, FOXC2, KDR, KRT14, and TEK, the mRNA expression ratio of cancer pathway-associated genes in the astrocytoma grade III cell line (SW1088) was comparable to that of other tumour cell lines." (PMID 36142793, 2022).
benign fibroma (1 paper, 2019). "All the malignant cells expressed KRT14 at assay commencement, with no expression detected in benign fibroma, normal ovary, or LP9 mesothelial cells." (PMID 31443478, 2019).
cataract (1 paper, 2018). Partial or complete opacity of the crystalline lens of one or both eyes that decreases visual acuity and eventually results in blindness.
cervical tumors (1 paper, 2025). "However, integrated HPV31 genomes from several cervical tumors overlap integration hotspots, including those on chromosomes 3 and 17 that contain the KLF5/KLF12 and KRT9/KRT14 genes, respectively." (PMID 40892869, 2025).
cystic fibrosis (1 paper, 2016). Autosomal recessive disorder caused by pathogenic variants in the CFTR gene (cystic fibrosis transmembrane conductance regulator), which encodes a chloride and bicarbonate channel expressed in epithelial cells, and follow the diagnosis criteria. "KRT14 and KRT8 was previously found to be overexpressed in cystic fibrosis at both RNA and protein level." (PMID 27533088, 2016).
Diffuse alveolar damage (1 paper, 2017). Diffuse alveolar damage (DAD) describes a common histologic injury pattern of the lung. "We have previously showed that Keratin 14 (KRT14) is overexpressed in human lung alveoli during diffuse alveolar damage (DAD), while normal lung do not." (PMID 28199407, 2017). "We recently observed Keratin 14 (KRT14) expression during diffuse alveolar damage (DAD), but not in controls." (PMID 28199407, 2017).
endocervical carcinoma (1 paper, 2023). A carcinoma that arises from epithelial cells of the endocervix. "As the expression of KRT14 and CLDN3 showed high consistency in both scRNA‐seq and 3D organoids, exhibiting clinical value, we further verified their heterogenous expression using TCGA cervical and endocervical cancer (CESC) dataset and clinical samples from our center." (PMID 36725337, 2023).
endometrial cancer (1 paper, 2017). Primary or metastatic malignant neoplasm involving the endometrium (mucous membrane that lines the endometrial cavity). "Overall, our data suggested that the gene expression of KRT14 (but not the antibody) is a marker for SCCs in endometrial cancer." (PMID 29079795, 2017).
esophageal cancer (1 paper, 2015). A primary or metastatic malignant neoplasm involving the esophagus. "The KRT14 is known to be downregulated in the esophageal cancer; however, we found it to be upregulated in the HNSCC from our patients." (PMID 25575813, 2015).
food allergy (1 paper, 2025). Gastrointestinal disturbances, skin eruptions, or shock due to allergic reactions to allergens in food. "In pediatric patients with AD, KRT5, KRT14, KRT16, FLG breakdown products, and AD clinical severity were predictive of concomitant food allergy." (PMID 40141720, 2025).
gastritis (1 paper, 2025). Inflammation of the stomach. "Meanwhile, for gastritis vs. non-gastritis classification, the highest mAUROC was again obtained with KRT14 (mAUROC = 72.3%, 55.8–88.8% (95% CI))." (PMID 41155404, 2025). "The best model for gastritis vs. non-gastritis classification combined H. pylori status with the plasma concentrations of ARG1, KRT14, and F13A1, yielding an mAUROC of 82.2% (64.1–99.9% (95% CI))." (PMID 41155404, 2025).
gingival overgrowth (1 paper, 2020). Excessive growth of the gingiva either by an increase in the size of the constituent cells (gingival hypertrophy) or by an increase in their number (gingival hyperplasia). "Its function in this site is unclear, but Keratin-14:Cre driven epithelial ablation of FAM20A is sufficient to induce gingival overgrowth in mice." (PMID 33425910, 2020).
interstitial lung disease (1 paper, 2017). A diverse group of lung diseases that affect the lung parenchyma. "Quantitative PCR and Western blot analyses highlighted the presence of KRT14 (mRNA and protein) only in human lung samples with DAD or interstitial lung disease (ILD)." (PMID 28199407, 2017).
keratoconjunctivitis (1 paper, 2017). Inflammation of both the cornea and the conjunctiva. "In a transgenic mouse line hK14mIL33tg, with the expression of interleukin-33 (IL-33) driven by a keratin 14 promoter, keratoconjunctivitis developed spontaneously between 18 and 22 weeks of age under specific-pathogen-free conditions." (PMID 28855579, 2017).
non-small cell lung carcinoma (1 paper, 2015). A group of at least three distinct histological types of lung cancer, including non-small cell squamous cell carcinoma, adenocarcinoma, and large cell carcinoma. "Further, PDX tissue sections generally did not express antigens characteristic of non-small cell lung cancers, including Keratin 5, Keratin 6, Keratin 7, Keratin 14, Keratin 20, TTF1, TP63, and Napsin A." (PMID 25955027, 2015).
pemphigus (1 paper, 2021). Pemphigus is a group of rare autoimmune diseases that cause blistering of the skin and mucous membranes (mouth, nose, throat, eyes, and genitals).This conditioncan occur at any age, but often strikes people in middle or older age. "KRT14, a marker of keratinocytes, was significantly higher, and PECAM1, a marker of endothelial cells, was significantly lower in pemphigus cases vs. controls." (PMID 34660634, 2021).
plasmacytoma (1 paper, 2016). Plasmacytoma is a localized mass of neoplastic monoclonal plasma cells that represents approximately 5% of all plasma cell neoplasms. "Furthermore, cytokeratin 14 and E7 were expressed in cultured K14E7 Fancd2−/− marrow and nonadherent cells subcultured in Interleukin-3 (IL-3) generated factor-independent (FI) malignant plasmacytoma cell lines." (PMID 27637088, 2016).
prostate adenocarcinoma (1 paper, 2017). "Within this group of genes, Ets2 (V-ets erythroblastosis virus E26 oncogene homolog 2) and Skp2 (S-phase kinase-associated protein 2, p45) were identified as proto-oncogenes, and Krt14 (Keratin 14) is a structural protein that is widely used as a marker for prostate adenocarcinoma." (PMID 28874141, 2017).
Pruritus (1 paper, 2025). Pruritus is an itch or a sensation that makes a person want to scratch. "Interestingly, cultured murine keratinocytes carrying the mutation krt14 R131P, homologous to the human KRT14 R125P, revealed up-regulation of the cytokine thymic stromal lymphopoietin (TSLP), which correlates with pruritus." (PMID 40700032, 2025).
scleroderma (1 paper, 2022). Scleroderma is a rare autoimmune connective tissue disorder characterized by abnormal hardening of the skin and, sometimes, other organs. "Immunofluorescence stainings revealed that the expression levels of epidermal stem cell markers (KRT14 and TP63) and mature epidermal marker (KRT10) were downregulated in scleroderma, while these proteins were recovered to normal levels in the treatment group." (PMID 35315234, 2022).
systemic sclerosis (1 paper, 2022). A chronic disorder, possibly autoimmune, marked by excessive production of collagen which results in hardening and thickening of body tissues. "Morphea patients also exhibited increased Cytokeratin 14 and DSG4 antibodies compared to healthy controls and systemic sclerosis cases by NFI." (PMID 35073943, 2022).
tongue (1 paper, 2023). "In our previous study, we identified the concurrent expression of cytokeratin-14 (CK14) in vimentin-positive early-stage tongue SCC cells." (PMID 36831453, 2023).
ulcers (1 paper, 2020). "The mice had severe pruritus and scratched frequently which led to skin erosions and ulcers necessitating euthanasia at 8–10 weeks of age for the BALB-CMV Sharpin-/- and Krt14 Sharpin-/- mice." (PMID 32687504, 2020).
Umbilical hernia (1 paper, 2020). Protrusion of abdominal contents through a defect in the abdominal wall musculature around the umbilicus. "From this set of genes, we highlight KRT14 (Keratin 14), CCBE1, ACAN, Desmoglein 2 (DSG2) and EPYC, which were more enriched in the anatomic development process in the gene network and were upregulated in animals affected by umbilical hernia." (PMID 32379844, 2020).
urothelial bladder carcinoma (1 paper, 2021). "NanoString-based gene expression analysis using typically luminal (GATA3+/KRT20+) and basal markers (KRT14+/KRT5+/GATA3low/-/KRT20low/-) classified urothelial bladder carcinoma samples as luminal, basal, and a third category (KRT14-/KRT5-/GATA3-/KRT20-), null/double negative (non-luminal/non-basal)." (PMID 34771663, 2021).